ERBB2 (erb-b2 receptor tyrosine kinase 2)
Diseases named in the same sentence as ERBB2 in open-access papers (continued):
Sharing a sentence is not in itself a finding about the gene and the disease.
breast cancer (continued). "Thus, our data are consistent with a model whereby ErbB2-dependent ERK activation downregulates IRF6, IRF6 downregulation causes reduction in the cellular BLNK levels, whereas BLNK loss in turn inactivates p38MAPK and thus blocks breast cancer cell anoikis." (PMID 35933456, 2022). "In addition, Vimentin is overexpressed in various epithelial cancers, including prostate cancer, gastrointestinal tumors, tumors of the central nervous system, breast cancer, malignant melanoma, and lung cancer, indicating that ERBB2 promotes ESCC cell migration." (PMID 35524932, 2022). "In addition to histopathological characterization, breast cancers are classified according to the presence of estrogen receptors (ERs), progesterone receptors (PRs), and human epidermal growth factor receptor−2 positive (ERBB2/HER2+)." (PMID 36232636, 2022). "Moreover, novel proteasome inhibitors are now being developed for solid tumor treatment and could be explored as BLNK-upregulating drugs in ErbB2-positive breast cancer." (PMID 35933456, 2022). "Thus, we tested whether BLNK upregulation blocks the ability of ErbB2-positive breast cancer cells to form tumors in mice." (PMID 35933456, 2022). "Our findings suggest that increasing BMI might be associated with a higher genomic risk in younger patients with ER-positive, ERBB2-negative breast cancer." (PMID 36441548, 2022). "This nonrandomized clinical trial aimed to evaluate the feasibility of the pertuzumab, atezolizumab, docetaxel, and trastuzumab (PATH) combination as a neoadjuvant treatment in patients with ERBB2-positive early breast cancer and whether it warrants continuation to the next phase." (PMID 35797012, 2022). "Thus, we decided to test whether the activation of ERBB4 signaling by neuregulins may restrain the aggressiveness of HER2+ breast cancers, if ERBB2 is inhibited by anti-HER2 agents." (PMID 35664762, 2022). "By blocking the Akt signaling pathway and increasing DNA breakage, the HDAC Class I inhibitor sNDX-275 can significantly promote Trastuzumab-induced growth inhibition in erbB2-overexpressed breast cancer cells, which may also overcome Trastuzumab resistance in breast cancer immunotherapy." (PMID 35585975, 2022). "Given their advanced pharmaceutical properties, next-generation HER2-targeted ADCs have the potential to be active beyond traditional HER2-positive breast cancer and may be effective in cells with low expression of HER2 or ERBB2 mutations, opening a spectrum of new possible clinical applications." (PMID 34380530, 2021). "In the current study, we explored whether a CNN weakly supervised by tumor ERBB2 gene amplification status as determined by chromogenic in situ hybridization (CISH) and trained with standard hematoxylin and eosin (H&E) stained tissues samples, can predict breast cancer ERBB2 status." (PMID 33597560, 2021). "Consistently, previous studies had showed that CD151 ablation can sensitize multiple tumor cell types to gefitinib by increasing cells apoptosis and disruption of CD151 can sensitize breast cancer cells to ErbB2 inhibitors, this findings also confirmed our hypothesis." (PMID 34108040, 2021). "Similarly, ERBB2 (HER2) amplification plays a pivotal role in breast cancers." (PMID 34527193, 2021). "Furthermore, this promotion of autophagy contributes to the resistance of ERBB2 expression to cell death induced by stresses such as chemotherapy drug treatment in breast cancer cells, which provides insight into proper strategies for the treatment of cancers expressing ERBB2 by targeting autophagy." (PMID 33801244, 2021). "Besides the co-amplification with ERBB2 in breast cancer, the SRCIN1 gene might be lost or disrupted in some cases of aggressive neuroblastoma due to the 17q12 chromosomal rearrangement." (PMID 34708040, 2021). "Thus, whether and how autophagy regulated by the ErbB2-DEPTOR axis contributes to ErbB2-targeted therapies is an interesting topic to further explore using mouse model of breast cancer." (PMID 33854045, 2021).
breast cancer (continued). "Indeed, ErbB2 gene amplification is one of the most frequent genetic events in breast cancer, resulting in the overexpression of HER2, which promotes cell proliferation predominantly through the activation of the mitogen-activated protein kinase (MAPK) pathway." (PMID 33204027, 2021). "Thus, we supposed that circ-ERBB2 might exert its oncogenic function in HER2-positive breast cancer by sponging miR-136-5p or miR-198." (PMID 34732216, 2021). "The prognosis of receptor-mediated targeted therapy in breast cancer is mainly dependent upon the extent of overexpression of the breast cancer-specific cellular receptors particularly human epidermal growth factor receptor-2 (HER2/Neu/ErbB2), estrogen and progesterone receptors." (PMID 34959321, 2021). "Our findings reveal new insights into mechanisms that control the surface expression of overexpressed ErbB2 and suggest that reduced CHIP expression may specify ErbB2-overexpressing breast cancers suitable for combined treatment with Trastuzumab and ER stress inducing agents." (PMID 34439093, 2021). "Triple-negative breast cancer is more likely to recur as compared with other breast cancer subtypes, with five-year specific survival rates of 85% for stage 3 triple-negative cancer, as compared with survival rates ranging from 94-99% for hormone receptor-positive and ERBB2-positive cancers." (PMID 35096628, 2021). "Similar to EREG, drugs that interfere with AREG, particularly in chemoresistant breast cancers, effectively acquiesce tumor growth, tumor-associated macrophage (TAM) infiltration and block the activation of diverse EGF receptors (ErbB1, 3 and 4+ ErbB2 HER2/Neu)." (PMID 34299315, 2021). "ErbB2’s clinical link with the functioning of the heart was reported in a study where 27% of the patients who received doxorubicin and anti-ErbB2 (trastuzumab/herceptin) for breast cancer with overexpression of ErbB2 subsequently developed synergistic cardiac toxicity." (PMID 34681194, 2021). "Thus, our findings that ECD is required for the nuclear export of the mRNA for this driver oncogene and to maintain high ErbB2 mRNA and protein levels in ErbB2-overexpressing breast cancer cells suggested the strong likelihood that ECD would be required for ErbB2-driven oncogenic traits." (PMID 33941617, 2021). "Currently, breast cancer is classified into five major categories (normal-like, luminal A, luminal B, Her2-positive and basal-like) based on expression of three receptors: oestrogen and progesterone hormonal receptors (ER and PR) and the epidermal growth factor receptor ERBB2 (Her2)." (PMID 33845831, 2021). "To further determine the clinical pertinence of NLGN2 in breast cancer, we assessed its prognostic performance in different intrinsic subtypes with or without the estrogen receptor (ER), progesterone receptor (PR) and Erb-B2 receptor tyrosine kinase 2 (HER2) expression." (PMID 34804909, 2021). "Thus, the discovery of small molecules targeting the interaction between DEPTOR and ErbB2 might be an attractive approach for ErbB2-positive breast cancer therapy." (PMID 33995662, 2021). "As a first step in this direction, we utilized public in vitro viability panels with 90 experimental or approved therapeutic compounds and 84 breast cancer cell lines representing 35 luminal, 27 basal, 10 claudin-low, 9 normal and 3 of unknown subtypes, with 27 of them ERBB2 amplified." (PMID 33648460, 2021). "Collectively, these results demonstrate that Bortezomib could indeed elevate ER stress in ErbB2-overexpressing breast cancer cells and that this effect was more pronounced in CHIP-low cells, supporting the rationale to test the effect of this inhibitor against control vs. CHIP KD tumor cells." (PMID 34439093, 2021).
breast cancer (continued). "Specifically, ERBB2+ breast cancer can have 25 to 50 copies of the ERBB2 gene, resulting in a 40- to-100-fold increase in ERBB2 receptor expression in comparison to normal cells, hence why ERBB2 is targeted by anti-ERBB2 antibodies and, more recently, immunotherapy." (PMID 33670942, 2021). "Furthermore, epitope mapping studies of rat ErbB2/HER2 led to the discovery of several novel helper T epitopes, a subset of which also elicited strong Th1-dominated responses and therapeutic activity in the murine breast cancer model." (PMID 34579275, 2021). "Moreover, overexpression of ERBB2 leads to increased breast cancer metastasis." (PMID 34259866, 2021). "Lapatinib (Tykerb®, GlaxoSmithKline, London-Brentford, UK) is such an inhibitor targeting the receptor tyrosine kinase and EGFR-member ErbB2 to treat breast cancer (BC)." (PMID 33917267, 2021). "Furthermore, our systematic interrogation of these tumors contradicts the heterogeneous staining observed with established IHC and FISH clinical markers for ER, PR and ERBB2 and highlights the variety of fixed and shared genomic lesions in these three distinct breast cancer cases." (PMID 34011996, 2021). "However, ERBB2 amplification was newly detected in four samples and ERBB2 mutations were detected in five HER2-negative breast cancer samples." (PMID 33274848, 2020). "Finally, is a Boolean model of breast cancer with an emphasis on ERBB2 overexpression." (PMID 32527218, 2020). "We found that prenatal exposure to low doses of BPA promoted mammary tumor development in this clinically relevant model, which was preceded with significant alterations in epithelial cell proliferation, morphogenesis, and signal transduction in ER and erbB2 pathways in premalignant mammary tissues." (PMID 32353937, 2020). "Thus, LRIG1 may be an influential determinant of all the major subtypes of breast cancer, including ER-positive, ERBB2-positive, and basal-like breast tumors." (PMID 32448168, 2020). "Inthe Russian female population in 2017, breast cancer accounted for 21.1% ofmalignant neoplasms; the number of patients with stage I–II of thedisease amounted to 69.9%.Overexpression of the epidermal growth factor receptor ErbB2 was detected in asignificant percentage of the tumors." (PMID 32742732, 2020). "Having observed the potentiating effects of USP2 inhibition toward 17-AAG-induced ErbB2 downregulation, we reasoned that the USP2 inhibitor ML364 might sensitize ErbB2-positive breast cancer cells to HSP90 inhibition and accordingly investigated the effectiveness of the combined treatment." (PMID 32327714, 2020). "For similar reasons, the ErbB2 monoclonal antibodies (Trastuzumab) that are used to treat Her2+ breast cancer, or the molecules (e.g., recombinant NRG1β and anti-ErbB4 antibodies) that are currently in development for heart disease and cancer might not be useful for neurodevelopmental disorders." (PMID 32546684, 2020). "Some invasive forms of breast cancer (i.e. locally advanced breast cancer) presented a twofold higher incidence than the others, suggesting an urgent improvement of Trastuzumab (HerceptinTM) delivery toward erbB2 tyrosine kinase receptor (HER-2) found overexpressed in ∼25%–30% of breast cancers." (PMID 32195232, 2020). "Similarly, the discovery of epidermal growth factor receptor 2 (HER2/ERBB2) overexpression on the surface of breast cancer cells led to the development of the monoclonal antibodies trastuzumab and pertuzumab, now part of standard care for HER2 positive patients." (PMID 32374727, 2020). "In addition, segments surrounding the amplified locus may be amplified independently or lost, a fact well-illustrated by the gene encoding for topoisomerase II at 17q12, which is commonly amplified or lost in ERBB2-amplified breast cancers." (PMID 32987805, 2020).
breast cancer (continued). "Thus, the relationshipbetween overexpression and/or amplification of ErbB2 and a poor clinicalprognosis suggests that ErbB2 is an important link in the molecular biologicalclassification of breast cancers and an important therapeutic target.Currently, there are drugs whose action targets ErbB2." (PMID 32742732, 2020). "Moreover, ERBB2 mutations identified in the present study have not been reported in the breast cancer previously." (PMID 33732635, 2020). "For example, unlike in human breast cancers, the clinical benefits of Her2 amplifications and their association with Her2 overexpression are not straightforward in CMTs9,10, putting into question the incidence and potential clinical utility of ERBB2 amplification in CMTs." (PMID 32680987, 2020). "However, in our studies of MZF1 post-translational modification and their effect on protein stability, we found that in ErbB2-expressing breast cancer cells, MZF1 is a very stable protein and its stability was not affected by mutating its SUMO sites (Brix and Kallunki, unpublished observations)." (PMID 31963147, 2020). "Additionally, NDGA inhibits tumor-relevant receptor tyrosine kinases and downstream signaling related to the IGF-1 receptor and the downstream protein serine/threonine kinase AKT, along with the c-ErbB2/HER2/Neu receptor in breast cancer cells and in tumor-bearing mice." (PMID 32184727, 2020). "Gene expression profiling enables the classification of breast cancer into distinct molecular subtypes with prognostic significance based upon histological grade and the status of estrogen receptor (ER), progesterone receptor (PgR), and HER2/neu expression (HER2 or ErbB2)." (PMID 32185126, 2020). "There was a phase 2 trial that demonstrated that women with high risk, stage II/III, ERBB2-negative breast cancer had improvement in pathological complete response (pCR) rate when pembrolizumab was added to standard neoadjuvant chemotherapy over patients who received chemotherapy alone." (PMID 33680917, 2020). "Therefore, CHD4 should be considered a potential target in ERBB2+ breast cancers." (PMID 30967373, 2019). "Knowing that ERBB2 and TOP2α genes are located in the same chromosome in human and cat genomes, we analyzed the DNA copy number of ERBB2 and TOP2α genes in a collection of feline mammary tumors (n=27), always in comparison with the disease-free tissue from the same individual." (PMID 31301170, 2019). "Thus, while the de-repression of protein-coding PRC2 target genes in NIC/c-SrcL/L cells is limited, a core subset of these genes may be regulated by PRC2 in human ERBB2+ breast cancer." (PMID 31263101, 2019). "Thus, we wonder whether asporin could regulate Met and ErbB2 signaling pathways in cancer, especially in breast cancer." (PMID 31608236, 2019). "Thus, targeting Tregs during anti-p185erbB2 targeted therapy may represent a therapeutic benefit to erbB2 driven breast cancer patients." (PMID 30800128, 2019). "Additionally and in a near future, the accurate evaluation of ERBB2 expression will have great value improving targeted treatments in cats with ERBB2-positive mammary tumors, especially, with the recent licensing of TKI’s for small animal practice and development of felinized anti-ERBB2 antibodies." (PMID 31301170, 2019). "Human breast cancer cells or mammary epithelial cells with a high expression of receptor tyrosine-protein kinase ERBB2 exhibited an enhanced response to ethanol-stimulated cell invasion in vitro, therefore ethanol stimulates ROS production in mammary epithelial cells in an ERBB2-dependent manner." (PMID 30611309, 2019). "Therefore, inhibiting p130Cas/ErbB2 interaction might represent a new therapeutic strategy to target breast cancer." (PMID 30816273, 2019).
breast cancer (continued). "As cellular cholesterol levels were shown to regulate metastatic phenotypes of cancer cells by altering the fluidity of cell membranes, we investigated whether the differential cholesterol amounts in ErbB2-positive breast cancer cells correlated with their migratory abilities." (PMID 30786890, 2019). "Additionally, an implication in ERBB2-positive breast carcinomas is indicated." (PMID 31796128, 2019). "The diagnostic of amplification in the ERBB2 oncogene leading to the overexpression of the HER2 protein constitutes a paradigm for the use of biomarkers in oncology since trastuzumab, an anti-HER2 antibody, have revolutionized the outcome of ERBB2-amplified metastatic breast cancer patients." (PMID 29515767, 2018). "To test whether ErbB2 downregulates Irf6 in human ErbB2-positive breast cancer cells, we examined the effect of ErbB2 inhibitors, such as the anti-ErbB2 antibody trastuzumab or the ErbB2/epidermal growth factor receptor small-molecule inhibitor lapatinib, on Irf6 in these cells." (PMID 30545388, 2018). "Thus, ErbB2 downregulates Irf6 in detached human breast cancer cells." (PMID 30545388, 2018). "Because ErbB2 overexpression renders breast tumor cells anoikis-resistant, mechanisms of this resistance are potential novel targets for treatment of ErbB2-positive breast cancers, and mediators of this resistance are potential biomarkers of breast tumor sensitivity to ErbB2 antagonists." (PMID 30545388, 2018). "The combination of clinical and molecular information may enhance the prognostic value for distant recurrence and risk stratification in estrogen receptor–positive, ERBB2-negative breast cancer, particularly for women with node-positive disease." (PMID 29450494, 2018). "Furthermore, we found that the anti-ErbB2 antibody trastuzumab used for ErbB2-positive breast cancer treatment upregulates Irf6 in BT-474 cells much more noticeably than in their variant selected for trastuzumab resistance by prolonged cell exposure to trastuzumab in 3D culture." (PMID 30545388, 2018). "Recent data showed that MET in combination with trastuzumab killed cancer stem cells and inactivated ErbB2/IGF-1R interactions in a synergistic manner via inhibiting Src kinase and/or PI3K/Akt pathway, causing overwhelming primary resistance to trastuzumab in HER2 positive breast cancer cells." (PMID 30483391, 2018). "Interestingly, interaction with MACF1 would strengthen the link of Teneurins with ERBB-mediated signaling, as in breast cancer cells, ß-heregulin could induce ERBB2-dependent protrusions that were enriched in microtubules." (PMID 30618566, 2018). "Importantly, ErbB2 causes loss of all p63 isoforms in a mouse model of breast cancer, and none of the p63 isoforms are expressed in human breast tumors." (PMID 30545388, 2018). "Furthermore, high intra-tumoral levels of immune-related genes, including those associated with type I interferon responses, and the presence of CD8+ cytotoxic T lymphocytes, correlate with improved disease outcome in patients with ERBB2+ breast cancer and TNBC." (PMID 30254632, 2018). "Thus, we investigated (i) the expression of different epigenetic markers, (ii) the effect of epigenetic modifying agents on the expression of ERα and HER2/ERBB2 and (iii) the effect on the response to tamoxifen in four breast cancer cell lines with different hormonal receptor status." (PMID 30583472, 2018). "Thus, in HER2/ERBB2-driven breast cancer, hypoxia-induced HIF-1 promotes HER2 inhibitor lapatinib resistance via inhibiting MAPK phosphatase dual-specificity phosphatase (DUSP2) expression, thereby compensating the loss of MAPK activity in lapatinib-treated cells." (PMID 28841148, 2017). "However, the effect of miR-1296-5p in ERBB2-positive breast cancers remains obscure." (PMID 29089858, 2017). "Thus, one function of Mek in detached breast cancer cells is to support ErbB2 expression." (PMID 29285258, 2017).